NOTCH3 (notch receptor 3)
Diseases named in the same sentence as NOTCH3 in open-access papers (continued):
Sharing a sentence is not in itself a finding about the gene and the disease.
tumor (continued). "Increased Notch3 protein levels have been identified as a prognostic marker for patients with PDAC, and lead to increased tumor invasion, metastasis, and shortened patient survival." (PMID 28922540, 2017). "The endostatin (E) and CTX (C)-treated samples exhibited almost similar expression levels for NOTCH-3, JAG-1, and DLL-4 that confirms the additive effect of the combination therapy against tumor angiogenesis." (PMID 26762567, 2016). "For instance, the fully human IgG2 antibody Tarextumab (TRXT, OMP59R5) combined with chemotherapy has been shown to significantly reduce tumor recurrence in patient-derived SCLC xenografts, by targeting Notch2/Notch3." (PMID 27847554, 2016). "The significant direct correlation observed between Pin1 and Notch3 expression levels in human T-ALL cell lines and primary tumor samples confirms the possible relevance of our observations for human T-ALL development." (PMID 26876201, 2016). "We showed NOTCH3 expression in CAFs by immunohistochemical study of samples of 93 cases of human tongue OSCC and found that NOTCH3-positive CAFs promote tumor angiogenesis in the presence of various cancer cell lines in vitro." (PMID 27124156, 2016). "However, whether Notch3 plays a role in tumorigenesis or tumor progression is unclear." (PMID 25668819, 2015). "We confirm it modulates differentiation and expression of important tumor-promoting signaling pathways in macrophages, such as NFκB, STAT3, Notch 3 and IRAK1." (PMID 25599228, 2015). "These genes included tumor markers (MUC16), genes that control tumor migration (MYL9), metastasis (CEACAM6, VEGFC, CX3CL1, CST1, CCL5, S100A9, IGF1, NOTCH3), cell adhesion (FN1, CEACAM1), and inflammation (TRAF2, NF-κB2 and RelB)." (PMID 26090868, 2015). "Since excessive Notch signaling activity is often toxic for several cell types, this result suggests that Notch3 hyper-activation is well tolerated in PAX3-FOXO1-harboring RMS cells and supports tumor growth." (PMID 24797362, 2014). "Both gene knockdown of Jagged-1 and transfection of the Notch3 intracellular domain (NICD3) suggest the existence of a juxtacrine loop that impacts ovarian cell-cell adhesion and tumor growth." (PMID 25072022, 2014). "The distinct methylation pattern of Notch3 and Hes5 genes in primary B cell leukemia compared to T-ALL further suggest that aberrant DNA methylation occur in a tumor specific and lineage-specific fashion." (PMID 23637910, 2013). "Interaction between Notch3 and other signaling pathways, including the Wnt, MAPK, and EFGR pathways, plays a key role in the growth and proliferation of various neoplasms." (PMID 23426998, 2013). "Expression of human N1C in pre-tumor thymocytes from the ROSA26 locus activated transcription of its known downstream targets such as endogenous Notch1, Hes1, Deltex1, c-myc and Notch3." (PMID 22393458, 2012). "In summary, this study has identified nuclear expression of Notch3 and HEY-1 in tumours as potentially useful indicators of poor prognosis in PDAC." (PMID 23226563, 2012). "Backward variable selection in a Cox model verified tumour size and histology, and the three molecular markers CD68, Gas6, and Notch3, as relevant factors." (PMID 21794149, 2011). "Moreover, compared to normal samples, HSPA6, NOTCH3, and PKP2 were dramatically overexpressed, while GPD1L and SMAD9 were dramatically de-expressed in tumor samples in both the LUAD training dataset and the LUAD validation dataset (all P < 0.05)." (PMID 40796704, 2025). "Similarly, miR-206 has been identified as a tumor-suppressive miRNA frequently downregulated in CRC, with its reintroduction reducing cell proliferation and migration through inhibition of Notch3 and c-Met signaling." (PMID 40943532, 2025). "NOTCH2, NOTCH3, and NOTCH4 may act as oncogenes in cSCC, with studies showing high expression of NOTCH2 and NOTCH3 in cSCC tumor tissues." (PMID 39925808, 2025).
tumor (continued). "Similarly, in the LUAD tumor group, HSPA6, NOTCH3, and PKP2 protein expression were dramatically stimulated, whereas GPD1L and SMAD9 protein expression were dramatically suppressed (all P < 0.05)." (PMID 40796704, 2025). "SIRT6 overexpression decreases NOTCH3 (Neurogenic locus notch homolog protein 3) levels in U87 cells, suggesting that SIRT6 may inhibit NOTCH3 expression, reducing its tumor-promoting effects." (PMID 40710366, 2025). "In addition, the expression of serum HSPA6, NOTCH3 and PKP2 were significantly up-regulated in the LUAD tumor group, while GPD1L and SMAD9 showed a significant down-regulation trend when compared to the control group." (PMID 40796704, 2025). "Additionally, NOTCH3’s interaction with the TME, particularly its influence on angiogenesis and the suppression of anti-tumor immune responses, facilitates tumor growth and metastasis." (PMID 39286249, 2024). "Finally, in the T-ALL context, Notch3-ICD undergoes deacetylation by HDAC1, favoring tumor development and progression in a Notch3-induced transgenic mouse model of T-ALL." (PMID 39684550, 2024). "The int-CAs showed higher expression of IR transcripts of NOTCH1 and NOTCH3 compared to the other tumor types but did not have the IR transcripts of NOTCH2 and NOTCH4 (p < 0.05)." (PMID 39101773, 2024). "The previous study has shown that PTENα/β promotes tumor progression in liver cancer cells by interacting with WDR5 to recruit the SET1/MLL complexes to the promoters of the PTENα/β-target genes, such as NOTCH3, SLC12A5 and TCF19, the broadly studied oncogenes." (PMID 38744853, 2024). "Consequently, we chose cancer types where the NOTCH3 expression level was substantially connected with the prognosis in GEPIA and considerably adversely correlated with tumour purity in TIMER35." (PMID 38906903, 2024). "Our study illustrated that Notch3 could facilitate the progression of CRC by increasing the infiltration of macrophages and MDSCs to promote the immunosuppressive tumor microenvironment." (PMID 36647017, 2023). "This analysis confirmed that knocking down Notch3 selectively killed metastatic but not primary tumor cells." (PMID 37202533, 2023). "Of note, the use of bulk RNA sequencing data does not reveal the cell-intrinsic role of Notch3 in tumor cells." (PMID 36854682, 2023). "Using TCGA paired samples (normal and tumor), we then looked for methylation events in patients with a decreased Notch3 expression in the tumor sample (T/N < 1) and patients with no decreased Notch3 expression (T/N > 1)." (PMID 36854682, 2023). "The results suggest that the combination of metformin and evodiamine suppressed tumor growth of KLF10-deficient PDAC cells by elevating KLF10 and suppressing Notch-3/4 signals without any substantial toxicity." (PMID 37308977, 2023). "Other genes, such as NOTCH3 and SLITRK5, have clear contributions to tumor development." (PMID 37214090, 2023). "Notably, silencing IGF2BP3 potently impaired the stemness properties in NPC cell lines and lung metastasis in tumors, and these effects were abrogated by NOTCH3 overexpression, suggesting that IGF2BP3 promotes tumor metastasis through Notch3 pathway." (PMID 37853162, 2023). "The protein levels of NOTCH3 and RBP1 showed similar results between normal and tumor tissues." (PMID 36226177, 2022). "In order to evaluate whether MET levels are modulated after NOTCH signaling inhibition, we silenced NOTCH1 and NOTCH3, the two NOTCH receptors hyper-activated in our cell tumor context, in two FP-RMS (RH30 and RH4) and two FN-RMS (RD and JR1) cell lines." (PMID 35574376, 2022). "NOTCH3 itself can promote the apoptosis of tumor endothelial cells, independent of cleavage and transcription regulation." (PMID 35332121, 2022). "Exosomes released from drug-resistant tumor cells have been found to affect antiviral RIG-I (retinoic acid-inducible gene 1 enzyme) signaling and can be transferred to recipient tumor cells to increase drug resistance by affecting the NOTCH3 pathway." (PMID 35664698, 2022).
tumor (continued). "It was found that the administration of anti-Notch2 antibodies suppressed the development of HCC/CCC, while the administration of anti-Notch3 antibodies exhibited no such effects on tumor progression." (PMID 35064244, 2022). "Moreover, the expression of NOTCH3 and SMARCA4 were increased at tumor progression stages III and IV relative to that in the tumor progression stages I and II." (PMID 35900231, 2022). "Multivariate analysis (Cox’s proportional hazards regression model) showed that the possible independent prognostic factors for OS were as follows: Age, tumor location, local recurrence, tumor resection, WHO grade, Ki-67 expression, and ATRX expression, ASAP3 expression, and NOTCH3 expression." (PMID 36382054, 2022). "Moreover, Notch 3 is an oncogenic factor for ER+ and HER2+ human patients, but a tumor suppressor for TNBC cell lines and ERBB2 basal tumor cells." (PMID 35406423, 2022). "Unlike the neonatal vasculature, we observed NOTCH3 expression in the biologically active endothelium in a majority of human fetal organs, while EC NOTCH3 expression has been reported for tumor vessels." (PMID 34043714, 2021). "In the TE11* group, nuclear staining for NOTCH3 in tumor cells was modest in mice treated with PBS, and absent in those treated with 5‐FU." (PMID 34042293, 2021). "Tspan5 correlation analyses of TCGA tumour samples revealed that Tspan5 expression is positively correlated with the expression of ADAM10, Notch1, Notch2, Notch3, Notch4, Hey1, vimentin, N‐cadherin and Snail, whereas it is negatively correlated with E‐cadherin in HCC tissues." (PMID 33955149, 2021). "In addition, Notch3 signaling also upregulates the expression of Cyclin G1 and SUSD2, which contributes to both tumor metastasis and cisplatin resistance of OC." (PMID 34195229, 2021). "For in vitro studies, the role of IKBKE, IGF1R, NOTCH3 and MDM4 in tumorigenesis and tumour metastasis have been reported and have provided clinicians with potential insights for understanding the biological behaviour of TNBC and exploring treatment strategies for heavily treated patients." (PMID 34396843, 2021). "Mechanistically, high NOTCH3 expression correlated with a lower infiltration of activated CD8+ T cells and a higher infiltration of immunosuppressive cells including Tregs and M2 macrophages in the tumor microenvironment." (PMID 33479597, 2020). "The resected tumor tissues were stained with antibodies against NRF2 and NOTCH3." (PMID 33219226, 2020). "In summary, we show that the nuclear NOTCH2 inhibitor gliotoxin has global effects on the NOTCH signaling network in CLL cells, including the recovery of a newly identified non-canonical tumor suppressing NOTCH3 activity." (PMID 32570839, 2020). "Since extracellular YB-1 serves as a ligand for receptor Notch3 as well as TNFR1, this may contribute to aberrant signaling that promotes tumor development." (PMID 33255653, 2020). "Additionally, signaling cross-talk in squamous cell carcinoma involving NOTCH1 with the transforming growth factor beta (TGF-β) pathway represses NOTCH3 through zinc finger E-box binding homeobox 1 (ZEB1) and promotes EMT and tumor initiation." (PMID 33322834, 2020). "This is illustrated for example by studies on tumor initiation (Notch1; Notch3), stem cell control (Notch1; Notch4; Jag1; Jag2; DLL1), angiogenesis (Notch1; DLL4) invasion and metastasis in remote organs (Notch1; Notch2; Jag1; DLL1)." (PMID 32605277, 2020). "NOTCH3 inhibition is expected to efficiently reduce the recurrence of NRF2-activated cancers by suppressing tumor-initiating activities without having adverse effects on cancer-bearing hosts." (PMID 33219226, 2020). "In other tumor types, amplification of Notch3 drives Notch3 signaling activity independent of ligand activation." (PMID 32525899, 2020).
tumor (continued). "We were able to demonstrate that the GSI RO4929097 targets an unexpected non-canonical tumor-suppressing NOTCH3 activity, which is involved in spontaneous as well as gliotoxin-induced apoptosis in CLL cells." (PMID 32570839, 2020). "The suppressed tumor growth was restored by supplementation with the intracellular domain of NOTCH3 (N3ICD), supporting the notion that the NOTCH3 enhancer mediates the effects of hyperactivated NRF2 on tumor growth." (PMID 33219226, 2020). "Considerable inter-individual expression of NOTCH3 and miR-21 in tumor tissue, ranging from negative to strongly positive, has been reported, and increased expression of these molecules in PDAC has been suggested." (PMID 31652721, 2019). "The activation of doxycycline-inducible NOTCH1 and NOTCH3 in TT cells, through treatment with increased doses of doxycycline, has demonstrated a dose-dependent increase in NOTCH1, NOTCH3 and HES1 protein, a decrease in ASCL1 levels and ultimately a reduction in tumour growth in vitro and in vivo." (PMID 31443481, 2019). "Interestingly, the expressions of NOTCH1, NOTCH2 or NOTCH3 are highly correlated with those of many prognostic immune receptors, implying that Notch signaling might be important in the regulation of tumor immune response or tumor microenvironment, which, in fact, has been reported in many studies." (PMID 31185958, 2019). "Cell-specific analyses complemented these results by indicating that NOTCH1, NOTCH2 and NOTCH3 were up-regulated by TNFα in the tumor cells but not in the MSCs." (PMID 31105691, 2019). "All four NOTCH receptors mark this cell population, and, among them, NOTCH3 plays a nonredundant role in tumor propagation." (PMID 30060526, 2018). "Reduction of NOTCH3 expression impaired self-renewal capacity, resulting in a significant shrinkage of TNBC-M25 MPS, confirming the essential role of the NOTCH3 signaling pathway in promoting tumor stemness." (PMID 30180881, 2018). "Notch3 mRNA expression significantly increased in tumor tissue, compared with nontumor normal tissue (P < 0.0001)." (PMID 28568708, 2017). "Our results showed that the relative mRNA expression of Notch3 tumor samples is significantly higher than paired nontumor samples." (PMID 28568708, 2017). "To understand how the absence of Notch3 would impact the tumour vascularization, we studied in vitro human umbilical vein endothelial cells (HUVEC)." (PMID 28719575, 2017). "Our results revealed the tumor-suppressive character of KMT2A, NOTCH1, and NOTCH3 in U-87 MG cells." (PMID 28968975, 2017). "Tumor cell lines with high proliferation rates, poor differentiation and an aggressive clinical course, such as the TNBC cell lines MDA-MB-231 and BT549, presented lower expression levels of Notch3 and E-cadherin." (PMID 27841855, 2016). "In the present study, we focused on NOTCH3 expression in CAFs, not in tumor cells, and demonstrated that the expression of NOTCH3 in CAFs is associated with poor prognosis of OSCC patients." (PMID 27124156, 2016). "Our results from ΔCam × N3 double-tg mice show the tumour suppressor activity of NFATc1 in the experimental setting of hyperactive Notch, as it prevented T-ALL development despite these mice having constitutive Notch3 signalling." (PMID 27312418, 2016). "This suggests that either Notch2 or Notch3 inhibition can have therapeutic activity in SCLC cells or that non-cell autonomous effects on tumor stroma mediated by Notch2/3 inhibition are responsible for this effect." (PMID 27148486, 2016).
tumor (continued). "In line with their increased growth rate, tumor cells obtained from chemo-treated tumors displayed an augmented expression of the CSC-related genes ALDH1 and NOTCH3 compatible with a higher CSC content and supporting the evidence of a more aggressive phenotype of tumors following chemotherapy." (PMID 26247735, 2015). "Additionally, endothelial Jagged1 appears to exert an angiocrine function possibly by activating Notch3/Hey1 in tumor cells, promoting proliferation, survival and epithelial-to-mesenchymal transition (EMT), potentiating tumor development." (PMID 26213336, 2015). "Furthermore, the survival analysis indicated that Notch3 is a poor prognostic marker in HCC, which suggests that aberrant Notch3 expression is involved in the progression of the tumor." (PMID 25668819, 2015). "For example, while Notch1 is often oncogenic when expressed by cancer cells, Notch3 expressed by perivascular cells plays a major role in JAG1-mediated vascular function, and it is also important in Treg induction and expansion in the tumor microenvironment." (PMID 25309874, 2014). "We also noticed that the levels of Notch3 and HES1 were both correlated with proliferation markers in these tumors, suggesting that a hyper-activated Notch3-HES1 axis may contribute to tumor aggressiveness in vivo." (PMID 24797362, 2014). "Although we found a high correlation (r = 0.88; p < 0.001) between the expression ratios (Tumor/Normal) of NOTCH3 and Asef, no significant negative correlation was detected between miR-1 and NOTCH3 or Asef expression ratios in clinical specimens." (PMID 24244701, 2013). "Notably, NOTCH3 knockdown effectively attenuated this effect, substantially suppressing tumor growth in both stressed and non-stressed cohorts." (PMID 40940884, 2025). "Finally, while the five biomarker proteins (HSPA6, NOTCH3, PKP2, SMAD9, and GPD1L) are primarily intracellular, their presence in serum could potentially be attributed to tumor derived extracellular vesicles or cell lysis during tumor progression." (PMID 40796704, 2025). "Recent studied have shown that microRNA (miR)-136 binds directly to Notch receptor 3 (Notch3).Our bioinformatics analysis also showed that WWTR1-AS1 might interact with miR-136, which plays tumor suppressive roles by targeting Notch3 to suppress tumor cell stemness." (PMID 38331752, 2024). "Additionally, we observed that mATC cells overexpressed receptors such as FGFR1, EPHB2, PDGFRA, NOTCH3, ANTXR1, and NRP1, which could receive signals from CAFs and thereby promote tumor cell proliferation and aggressiveness." (PMID 37053016, 2023). "In addition, several studies demonstrated that forced Notch3 expression accelerated tumor formation in CRC xenografts while inactivation of Notch3 expression decreased cell proliferation, the clonogenic potential of CRC cells and tumor growth." (PMID 36647017, 2023). "Interestingly, Notch3 corrected UT-SCC-74B cells exhibited a slower growth rate as compared to the original UT-SCC-74B cells (p value < 0.0001) and resembled the UT-SCC-74A cell line derived from the primary tumor." (PMID 37202533, 2023). "However, this dataset contains a small number of normal unmatched tissues and we observed no decrease in Notch3 mRNA expression in the TCGA-BRCA dataset using matched tumor/normal samples." (PMID 36854682, 2023). "Notably, PTX treatment reduced the tumor sizes of S18 cells significantly but not S18 OE cells, indicating that enhanced NOTCH3 activation and signaling confers chemoresistance of NPC in vivo." (PMID 37563118, 2023). "Using RBPj-Notch reporter activation as an indicator for Notch activation and combining with specific Notch receptor antagonists, it was found that this effect proceeded from endothelial Dll4 signaling through Notch1, but not Notch3, in neighboring tumor cells." (PMID 33198378, 2020).